CD52 (CD52 molecule)
Diseases named in the same sentence as CD52 in open-access papers (continued):
Sharing a sentence is not in itself a finding about the gene and the disease.
asthma (3 papers, 2020 to 2024). "Because of its biological role in immune cells relevant to asthma as well as its potential translational implications, we, therefore, prioritized CD52 as a strong causal positional candidate gene for functional validation." (PMID 32296059, 2020). "Bioinformatics analyses prioritize candidate causal genes at 52 loci, including CD52, and demonstrate that asthma-associated variants are enriched in regions of open chromatin in immune cells." (PMID 32296059, 2020). "Another important aspect of our study is the in vivo functional validation of CD52 as potential candidate causal gene at the chromosome 1p36.11 locus, which may point to a role for the pathway involving this immune cell membrane protein in the development of asthma." (PMID 32296059, 2020). "Additionally, the identified childhood-onset asthma-associated gene of JAZF1 has evidence of genetic interactions with identified genes of AHI1, NSMCE1, TDRKH, CD52, and HLA-DRB1 based on a genome-wide map of genetic interaction inferred from radiation hybrid genotypes." (PMID 32867763, 2020).
B cell lymphoma (3 papers, 2018 to 2024). "Our results indicate that CD52 is expressed by a significant subset of these aggressive mature B-cell lymphomas, including those from patients with high-risk features and relapsed/refractory disease." (PMID 30020951, 2018). "Previous work has shown significant heterogeneity in CD52 expression by several of the more aggressive mature B-cell lymphomas (e.g. DLBCL, Burkitt lymphoma), with 25% of cases exhibiting negligible CD52 expression by immunohistochemistry." (PMID 30020951, 2018). "While CD52 expression was highly variable from case to case, convincing cytoplasmic and/or membranous expression was observed in the majority of both DHL (75%) and DEL (75%), at levels consistent with prior studies of aggressive mature B-cell lymphomas." (PMID 30020951, 2018). "Key metabolic pathways were blocked using representative inhibitors in a macrophage and humanized aggressive B cell lymphoma (hMB; cell line information see STAR Methods) co-culture-assay system, and phagocytosis was assessed through specific antibody targeting (alemtuzumab; anti-CD52)." (PMID 39603243, 2024).
Burkitt lymphoma (3 papers, 2015 to 2024). A rare form of malignant mature B-cell non-Hodgkin lymphoma. "ANT1034 was investigated in vivo in a repeat dose CD52+ Burkitt lymphoma mouse xenograft study." (PMID 26372145, 2015). "Applying human anti-CD52 IgG1-CAMPATH and IgG3-CAMPATH to WIEN-133 (human Burkitt’s lymphoma) cells induced CDC at higher EC50 values as compared to the respective anti-CD20 antibodies, and IgG3-CAMPATH reached only 30% of the maximum lysis of IgG1-CAMPATH." (PMID 39436656, 2024).
lymph node metastasis (3 papers, 2021 to 2024). "Additionally, we found that ESCC patients with lymph node metastases frequently had higher ID3 and CD52 expressions than ESCC patients without lymph node metastasis." (PMID 39256364, 2024).
lymphocytic leukemia (3 papers, 2021 to 2023). "Alemtuzumab, a humanized anti-CD52 antibody, has been used for depleting lymphocytic leukemia cells in patients with CLL." (PMID 34035227, 2021). "Finally, the CD52 gene must also be knocked out, to enhance the lifetime of the CAR-T cells in the presence of the lymphocytic leukemia medication alemtuzumab (which is an antibody that binds to CD52)." (PMID 37043430, 2023).
mantle cell lymphoma (3 papers, 2020 to 2023). Mantle cell lymphoma is a rare form of malignant non-Hodgkin lymphoma affecting B lymphocytes in the lymph nodes in a region called the ``mantle zone''. "In primary mantle cell lymphoma cells, a higher toxic effect with CD52 mAb was obtained, when cells were pretreated with ibrutinib, but only in an ibrutinib-sensitive cohort." (PMID 36587029, 2022). "Given the challenge of treating multi-resistant mantle cell lymphoma patients, this work highlights the potential use of anti-CD52 therapy as consolidation after ibrutinib treatment in patients who responded to the BTK inhibitor to achieve MRD negativity and prolong progression-free survival." (PMID 36587029, 2022).
multiple myeloma (3 papers, 2018 to 2023). "For example, plasma cell myeloma has shown both the acquisition and loss of CD52 expression over time, even in the absence of CD52-directed therapy." (PMID 30020951, 2018).
neutropenia (3 papers, 2019 to 2022). A decrease in the number of neutrophils found in the blood. "By acting on CD52, it also targets the innate immune system (by activation of pro-apoptotic pathways on macrophages and dendritic cells), at a risk of neutropenia and even pancytopenia, demanding frequent follow-up." (PMID 34358189, 2021). "Special mention should be made of late onset and potentially severe neutropenia, especially following anti-CD52 agent therapy." (PMID 31480527, 2019). "In this setting, transitory Grade 1–2 neutropenia related to biotherapy is relatively common with several biotherapies (e.g., TNF-alpha inhibitors, IL6 inhibitors, and anti-CD52 agents)." (PMID 31480527, 2019). "An approximate 10% prevalence of such neutropenia has been reported with several of these biotherapies (e.g., TNF-alpha inhibitors, IL6 inhibitors, and anti-CD52 agents)." (PMID 31480527, 2019).
Obesity (3 papers, 2021 to 2025). Accumulation of substantial excess body fat. "Interestingly, genomics studies indicate that CD52 is up-regulated in individuals with a phlegm-dampness constitution, and they have a much higher risk of obesity, metabolic syndrome, hypertension, and diabetes." (PMID 33705353, 2021). "All of these results further indicate that CD52 has important value for the study of obesity combined with T2DM." (PMID 33705353, 2021). "Taken together, our results complement the role of CD52 in obesity and metabolic diseases and offers a unique opportunity for the treatment of T2DM." (PMID 33705353, 2021). "On the other hand, pregravid obesity was associated with up-regulation of immunoregulatory molecules such as AHR (1.44-fold), CD52 (1.21-fold), and CD163 (1.8-fold)." (PMID 34195568, 2021). "Overall, CD52 may functioned as an important potential target for obesity with T2DM via TGF-β/Smad3 axis." (PMID 33705353, 2021). "High expression of CD52 in adipocytes may be an adverse biomarker for obesity and T2DM." (PMID 33705353, 2021). "Additionally, regulatory genes such as CD163, AHR, and CD52 were increased with pregravid obesity." (PMID 34195568, 2021). "The aim of the present study was to evaluate the involvement of CD52 in adipocytes as well as to explore its effect on type 2 diabetes mellitus (T2DM), and to improve our understanding of the potential molecular events of obesity with type 2 diabetes." (PMID 33705353, 2021). "Previous studies have shown that CD52 in blood is correlated with T2DM and obesity." (PMID 33705353, 2021). "However, to our knowledge, there are no reports on CD52 involved in obesity and T2DM in adipocytes." (PMID 33705353, 2021).
osteoporosis (3 papers, 2022 to 2024). A condition of reduced bone mass, with decreased cortical thickness and a decrease in the number and size of the trabeculae of cancellous bone (but normal chemical composition), resulting in increased fracture incidence. "Likewise, depletion of Omacs3 that represents the major senescent myeloid cells in bone using antibody against CD52 suppressed excessive bone loss in OVX SCID mice, which reinforces the importance of targeting senescent myeloid cells in osteoporosis." (PMID 39480497, 2024).
ovarian carcinoma (3 papers, 2009 to 2022). A malignant neoplasm originating from the surface ovarian epithelium. "For example, Tie2+ TAMs isolated from ovarian cancer patient ascites express high levels of CD52, the target of licensed IgG1 mAb Alemtuzumab (Lemtrada)." (PMID 35020853, 2022). "In a syngeneic ovarian cancer mouse model, anti-CD52 treatment was demonstrated to restrict tumour neo-angiogenesis and growth, substantiating the potential clinical utility of subset-level TAM-targeting." (PMID 35020853, 2022). "Targeting of these cells with anti-CCL2 antibody, anti-CSF-IR inhibitors, anti-CD52 antibody, and anti-CD11b antibody for therapy of ovarian cancer has been investigated in preclinical models of ovarian cancer." (PMID 30200478, 2018). "Anti-CD52 immunotherapy targeting VLC restricts tumor angiogenesis and growth in murine ovarian cancer." (PMID 19545375, 2009).
thyroid autoimmunity (3 papers, 2018 to 2024). "Also supporting an inhibitory role for CD52 is the observation that 20% and 3% of MS patients treated with lymphocyte-depleting alemtuzumab develop thyroid autoimmunity and autoimmune thrombocytopenia respectively within months or years after start of treatment." (PMID 33658999, 2020).
AL amyloidosis (2 papers, 2016 to 2022). AL Amyloidosis is a plasma cell disorder characterized by the aggregation and deposition of insoluble amyloid fibrils derived from misfolding of monoclonal immunoglobulin light chains usually produced by a plasma cell tumor. "SLAMF7, CD20, and CD52 were expressed in 98%, 38%, and 25% of AL amyloidosis cases with light chain‐restricted PCs as the amyloidogenic clone, respectively." (PMID 27109862, 2016).
Cirrhosis (2 papers, 2024). A chronic disorder of the liver in which liver tissue becomes scarred and is partially replaced by regenerative nodules and fibrotic tissue resulting in loss of liver function. "Although this study focused on circulating lymphocytes in acute decompensation of cirrhosis, a single-cell RNA sequencing atlas of cirrhotic and uninjured livers revealed upregulation of CD52 gene in CD4+ T cells in cirrhotic livers." (PMID 39276679, 2024). "The development of an alternative anti-CD52 antibody is required to restore T cell function and prevent infections in cirrhosis." (PMID 39276679, 2024). "The expression of CD52 in the peripheral blood lymphocytes of 49 patients with cirrhosis was investigated using flow cytometry and transcriptomics." (PMID 39276679, 2024). "This study aimed to investigate the function of CD52 on CD4+ T cells on the blood of patients with acute decompensation of cirrhosis." (PMID 39276679, 2024). "The upregulation of CD52 in the periphery of acute decompensation of cirrhosis hinders the recognition of the T cell receptor by MHC, contributing to impaired T cell function." (PMID 39276679, 2024). "CD52 expression was elevated in CD4+ T cells in acute decompensation of cirrhosis, and this elevation was correlated with increased disease severity and mortality." (PMID 39276679, 2024). "This study revealed an upregulation of CD52 expression in peripheral blood pan CD4+ T cells in patients with acute decompensation of cirrhosis, correlating with disease severity and 90-day mortality." (PMID 39276679, 2024). "Elevated CD52 contributes to adaptive immune dysfunction in acute decompensation of cirrhosis." (PMID 39276679, 2024). "Immune regulation by CD52 may be involved in adaptive immune dysfunction in cirrhosis." (PMID 39276679, 2024). "Considering that COL1A2 is a collagen, we performed a correlation analysis between SOX4, LGALS3, SERPINE2, CD52, LPXN, and MPP6 and the progression of cirrhosis." (PMID 39194690, 2024). "The development of a novel antibody targeting CD52 without T cell depletion could be a potential direction for immune therapy to prevent infections in cirrhosis." (PMID 39276679, 2024).
diabetes (2 papers, 2021). "To further confirm whether CD52 is involved in the pathogenesis of diabetes, we performed microarray analyses of CD4+CD52high T cells and CD4+CD52low T cells based on GSE94815." (PMID 33705353, 2021). "The results showed that CD52 expression levels were found to be significantly up-regulated in the preadipocytes of 3 obese patients without diabetes relative to 3 lean controls." (PMID 33705353, 2021). "Considering the elevated levels of CD52 expression in the adipocytes of obese and obese T2DM patients, it is likely that this may lead to an increase in the ratio of CD4+CD52high T cells to CD4+CD52low T cells, thereby promoting the development of diabetes." (PMID 33705353, 2021).
endometrial cancer (2 papers, 2020 to 2025). Primary or metastatic malignant neoplasm involving the endometrium (mucous membrane that lines the endometrial cavity). "Kaplan Meier plots using TCGA Endometrial Cancer database revealed that high mRNA expression of SCGB1D2, CD52, GNG2, GDNF, and SCUBE1correlated with favorable prognosis in EC patients (n=547)." (PMID 41262902, 2025). "Our results identified CD74, HLA-DRB5, CD52, HLA-DPB1 and HLA-DRB1 as possible valuable genetic markers for the diagnosis and prognosis of endometrial cancer and provided a theoretical basis for immunotherapy targets for its clinical treatment." (PMID 33159014, 2020).
Hepatic fibrosis (2 papers, 2022 to 2024). The presence of excessive fibrous connective tissue in the liver. "This study, focusing on LSECs and the molecular bases of endothelial dysfunction during liver fibrosis from different mice models, found that SOX4, LGALS3, SERPINE2, CD52, and LPXN are potential key genes associated with endothelial dysfunction in liver fibrosis." (PMID 39194690, 2024). "Subsequently, we conducted qRT-PCR analysis to examine the expression of five key genes (SOX4, LGALS3, SERPINE2, CD52, and LPXN) in the liver tissues of mice with liver fibrosis." (PMID 39194690, 2024). "CD52 and LPXN were moderately correlated with both liver fibrosis grade and liver disease progression, while MPP6 was weakly correlated with liver fibrosis grade and liver disease progression." (PMID 39194690, 2024). "Moreover, we identified five key regulatory genes for endothelial dysfunction in liver fibrosis LSECs: SOX4, LGALS3, SERPINE2, CD52, and LPXN." (PMID 39194690, 2024). "This study identified key regulatory genes for endothelial dysfunction in liver fibrosis, namely SOX4, LGALS3, SERPINE2, CD52, and LPXN, which will provide new targets for the development of therapeutic strategies targeting endothelial dysfunction in LSECs and liver fibrosis." (PMID 39194690, 2024). "Therefore, SOX4, LGALS3, SERPINE2, CD52, and LPXN may serve as key regulatory genes for endothelial dysfunction in liver fibrosis LSECs." (PMID 39194690, 2024).
interstitial lung disease (2 papers, 2022 to 2024). A diverse group of lung diseases that affect the lung parenchyma. "There are limited data on CD52 in fibrosis; we found a single study that showed an increased CD52 expression in alveolar macrophages in interstitial lung disease." (PMID 35159124, 2022).
LGL leukemia (2 papers, 2017 to 2022). "In frequent cases of LGL leukemia that are refractory to immunosuppressive agents or in early relapse, alemtuzumab, an anti-CD52 antibody, alemtuzumab, which is also the treatment of choice for T-cell prolymphocytic leukemia, was tested in LGL leukemia with several response cases." (PMID 35178350, 2022). "Besides, such immunosuppressive agents, like purine analogue (e.g. fludarabine in combination with dexamethasone) have had impressive response rate and Alemtuzumab (Campath), as a monoclonal antibody against CD52 is served as an effective therapy for LGL leukemia mostly with PRCA." (PMID 28427176, 2017).
liver cirrhosis (2 papers, 2022 to 2024). "By analyzing the Co-DEGs associated with the progression and prognosis of liver cirrhosis, we identified five key genes: SOX4, LGALS3, SERPINE2, CD52, and LPXN." (PMID 39194690, 2024).
liver disease (2 papers, 2024). "Although available, murine models do not fully recapitulate human liver disease, but they might provide further insights into potential mechanisms of disease pathogenesis that might account for the observed upregulation of CD52." (PMID 39276679, 2024).
myeloid leukaemia (2 papers, 2021 to 2023). "Taken together, our data suggested that genetically modified FLT3-ITD knock-in human myeloid leukemia K562 cells upregulated CD52 expression via activation of STAT5, and alemtuzumab showed an antitumor effect via induction of ADCC in K562–FLT3ITD/WT cells." (PMID 34035227, 2021).
myocardial infarction (2 papers, 2024). Gross necrosis of the myocardium, as a result of interruption of the blood supply to the area, as in coronary thrombosis. "A variation in the CD52 gene has been associated with a higher risk of myocardial infarction." (PMID 38474140, 2024).
myocarditis (2 papers, 2022 to 2024). Myocarditis is a condition that is characterized by inflammation of the heart muscle (myocardium). "Alemtuzumab, an antibody against CD52, is currently recommended in the treatment of myocarditis induced by ICI." (PMID 36358830, 2022). "In more severe cases of myocarditis, treatments such as abatacept (i.e., blocking CD80/86) or alemtuzumab (anti-CD52) can be administered." (PMID 39247203, 2024).
nephritis (2 papers, 2020 to 2023). Inflammation of renal tissue. "Correspondingly, we found a weak negative correlation between urine protein levels and plasma levels of soluble CD52 suggesting, as was observed with the nephritis cases, that patients with perturbed kidney function had deficient CD52 expression (n = 32; r = -0.213, p = 0.2421)." (PMID 33658999, 2020). "A humanized anti-CD52 monoclonal antibody, Alemtuzumab, has been approved for the treatment of relapsing multiple sclerosis, suggesting its potential benefit in nephritis." (PMID 38077419, 2023).
non-small cell lung carcinoma (2 papers, 2017 to 2021). A group of at least three distinct histological types of lung cancer, including non-small cell squamous cell carcinoma, adenocarcinoma, and large cell carcinoma. "Similar to CD52, CD3D is differentially expressed in the normal and malignant lung tissues of non-small cell lung cancer, consistent with our prediction." (PMID 34575089, 2021).
relapsing (2 papers, 2017 to 2018). "However, more marked (~75–90%) physical depletion of CD4 T cells by CD4 and CD52 depleting antibodies inhibited relapsing disease." (PMID 27925187, 2017).
alcoholic liver cirrhosis (1 paper, 2023). A disorder of the liver characterized by the presence of fibrotic scar tissue instead of healthy liver tissue. "In particular, clusters CD52 mono, C1QC macro, and SLC40A1 macro were more enriched in the PBMCs than in the liver tissues of patients with alcoholic liver cirrhosis." (PMID 36845083, 2023).
aplastic anemia (1 paper, 2017). Anemia resulting from bone marrow failure (aplastic or hypoplastic bone marrow). "Patients with aplastic anemia or hypoplastic myelodysplastic syndrome (MDS) may respond to immunosuppressive therapy, including the anti-CD52 antibody alemtuzumab." (PMID 27743175, 2017).
B-cell acute lymphoblastic leukemia (1 paper, 2020). A neoplasm of lymphoblasts committed to the B-cell lineage, typically composed of small to medium-sized blast cells. "Prior to initiation of these trials, two infants with relapsed refractory CD19+ B-cell acute lymphoblastic leukemia were treated with TALEN-mediated CD52 and TCR knockout CD19 CAR T cells in combination with anti-CD52 therapy." (PMID 32207531, 2020).
calcific aortic valve disease (1 paper, 2021). "The expression of SPP1, TNC, SCG2, FAM20A, and CD52 was all significantly up-regulated in calcific aortic valve disease." (PMID 34020624, 2021).
chronic myeloid leukemia (1 paper, 2025). "CD52 has been previously reported as upregulated during the blast crisis phase of chronic myeloid leukemia (CML)." (PMID 40868343, 2025).
epithelial ovarian tumors (1 paper, 2009). "Co-immunofluorescence on fresh frozen human epithelial ovarian tumors identified large CD52+/VE-Cadherin+ cells primarily in a perivascular location and in ovarian tumor stroma." (PMID 19545375, 2009).